DDX5 (DEAD-box helicase 5)
Diseases named in the same sentence as DDX5 in open-access papers (continued):
Sharing a sentence is not in itself a finding about the gene and the disease.
psoriasis (4 papers, 2018 to 2026). An autoimmune condition characterized by red, well-delineated plaques with silvery scales that are usually on the extensor surfaces and scalp. "In the present study, we found that the RNA helicase DDX5 was downregulated in keratinocytes from the inflammatory skin lesions in patients with atopic dermatitis and psoriasis, and that mice with keratinocyte-specific deletion of Ddx5 (Ddx5∆KC) were more susceptible to cutaneous inflammation." (PMID 36271146, 2022). "In lesions associated with AD and psoriasis, elevated IL-17D activates the CD93-p38 MAPK/Akt/Smad2/3 pathway, resulting in the downregulation of DEAD-box helicase 5 (DDX5) expression in keratinocytes." (PMID 40536951, 2026). "Based on immunoblotting and immunofluorescence staining, expression of DDX5 protein was reduced in whole skin lesions from patients with AD and psoriasis and slightly increased in epidermal tissues from skin carcinomas, compared with healthy skin." (PMID 36271146, 2022). "To address whether dysregulation of DDX5 function or expression had a role in propagating inflammation in the skin, we analyzed the expression profile of DDX5 in AD and psoriasis and generated mice with conditional knockout of Ddx5 in keratinocytes." (PMID 36271146, 2022).
tauopathy (4 papers, 2013 to 2023). Neurodegenerative disorders involving deposition of abnormal tau protein isoforms (tau proteins) in neurons and glial cells in the brain. "DDX5/RNA helicase p68 is reported to regulate tau exon 10 splicing by modulating the stem-loop structure at the 5′ splice site, and disruption of the regulation of tau exon 10 splicing plays an important role in the pathogenesis of tauopathy." (PMID 33408735, 2020).
acute lymphoblastic leukemia (3 papers, 2016 to 2025). Leukemia with an acute onset, characterized by the presence of lymphoblasts in the bone marrow and the peripheral blood. "Similarly, DDX5 is required in T-cell acute lymphoblastic leukemia (T-ALL) pathogenesis, which is evidenced by the decreased survival rate and inhibited proliferation following depletion of DDX510." (PMID 32690860, 2020).
male infertility (3 papers, 2021 to 2022). The inability of the male to effect fertilization of an ovum after a specified period of unprotected intercourse. "Together, these data reveal that germ cell‐specific knockout of Ddx5 leads to male infertility." (PMID 33666296, 2021).
neuroblastoma (3 papers, 2018 to 2026). Neuroblastoma (NB) is the most common solid, extracranial childhood tumor. "Analysis of neuroblastoma tumours in which tracRNAs are abundant revealed that low expression of DDX17 and DDX5 genes is associated with high-risk tumours and poor overall patient survival, and inversely linked with MYCN oncogene amplification." (PMID 42209732, 2026). "Here, we demonstrate that the transcriptional readthrough induced by DDX17 depletion, either alone or in combination with DDX5, leads to an increased production of chimeric transcripts from tandemly oriented gene, or tracRNAs, in neuroblastoma cells." (PMID 42209732, 2026). "NHEG1 inhibits the degradation of DDX5 through the ubiquitin–proteasome pathway to promote neuroblastoma progression." (PMID 35992805, 2022). "Collectively, our work reveals a novel function of MYCN in transcription termination and suggests that the deregulation of MYCN and DDX17/DDX5 expression in neuroblastoma may lead to the expression of non-canonical and potentially harmful RNA molecules." (PMID 42209732, 2026).
prostate tumors (3 papers, 2014 to 2021). "DDX5 acts as a novel androgen receptor interacting protein to induce prostatic tumor development." (PMID 33608512, 2021). "For example, the Ddx5 gene is fused in frame to the ETV4 gene in prostate tumors." (PMID 24275493, 2014).
rhabdomyosarcoma (3 papers, 2023 to 2025). A rare aggressive malignant mesenchymal neoplasm arising from skeletal muscle. "Given that RX-5902 is already under clinical investigation in other solid tumors, targeting DDX5 may offer a viable and selective therapeutic strategy for fusion-positive rhabdomyosarcoma." (PMID 40950397, 2025). "In alveolar rhabdomyosarcoma (ARMS), particularly in fusion-positive cases (FP-RMS), DDX5 plays a pivotal role in sustaining tumor growth and survival." (PMID 40950397, 2025). "In the context of rhabdomyosarcoma, and particularly in the fusion-positive (FP-RMS) subtype, DDX5 emerges as a central regulator of tumorigenesis, with implications for both disease progression and treatment." (PMID 40950397, 2025). "Interaction between DDX5 and YTHDC1 promotes the splicing of pre-mRNA into mature circRNA in rhabdomyosarcoma cells." (PMID 38062349, 2023). "In line with the observation that YTHDC1/DDX5 depletion reduces RMS proliferation, our results provide proteins and RNA candidates for the study of rhabdomyosarcoma tumorigenicity." (PMID 37019933, 2023).
small cell lung carcinoma (3 papers, 2022 to 2025). Small cell lung cancer (SCLC) is a highly aggressive malignant neoplasm, accounting for 10-15% of lung cancer cases, characterized byrapid growth, and early metastasis. "Interestingly, DDX5 depletion in small cell lung cancer (SCLC) inhibited the TCA cycle by reducing intracellular succinate (a direct electron donor to the mitochondrial complex II)." (PMID 35954483, 2022). "DDX5 is overexpressed in small cell lung cancer (SCLC) cell lines." (PMID 35992805, 2022).
triple-negative breast carcinoma (3 papers, 2019 to 2021). An invasive breast carcinoma which is negative for expression of estrogen receptor (ER), progesterone receptor (PR), and human epidermal growth factor receptor 2 (HER2). "RX-5902, an inhibitor that binds directly to phosphorylated DDX5, a post-translational modification of DDX5 which mediates epithelial to mesenchymal transition only in transformed cancer cells, is being studied in Phase I clinical trials for treatment of triple negative breast cancer." (PMID 34680866, 2021). "Our previous study revealed that TRIB3 can interact with DDX5/BNIP/BCLAF1 in radioresistant MDA-MB-231 cells; thus, it is involved in the self-renewal and radioresistance of triple-negative breast cancer cells by regulating Notch1 activation." (PMID 33334065, 2020).
Alzheimer disease (2 papers, 2022 to 2025). A progressive, neurodegenerative disease characterized by loss of function and death of nerve cells in several areas of the brain leading to loss of cognitive function such as memory and language. "Conversely, DDX5 downregulates NRGN, a gene crucial for synaptic plasticity and often associated with neurological and mental disorders, particularly Alzheimer’s disease, where it serves as a reliable biomarker for synaptic dysfunction." (PMID 41333436, 2025). "For example, we found that levels of ADAR, XRCC6 and SBDS were reduced in 5 of 7 Alzheimer’s disease samples and levels of DDX5, U2AF2, ILF3 were reduced in 4 of 7 Alzheimer’s disease NPC vasculature samples by greater than 50%." (PMID 36196083, 2022).
breast tumor (2 papers, 2023 to 2025). "The functions of ZC3H12D and DDX5 in breast tumor cell cycle regulation and tumor progression were determined in vitro and in vivo." (PMID 41263459, 2025). "In contrast to the ZC3H12D expression pattern, DDX5 protein expression was significantly increased in human breast tumor tissues, including luminal, HER2+, and TNBC subtypes." (PMID 41263459, 2025). "Overall, we unveiled a novel regulatory network in which ZC3H12D and DDX5 antagonistically regulate the mRNA stability and expression of cell cycle‐promoting genes in breast tumor cells." (PMID 41263459, 2025). "To define the effects of DDX5 on ZC3H12D‐induced CCND1 mRNA degradation, we overexpressed DDX5 in ZC3H12D‐overexpressing breast tumor cells and then performed an mRNA stability assay." (PMID 41263459, 2025). "In conclusion, our findings established that ZC3H12D and DDX5 play distinct anticancer and carcinogenic roles by modulating cell cycle progression in breast tumors." (PMID 41263459, 2025). "The results of the GO analysis also revealed that DDX5 regulated the expression of cell cycle‐related genes in breast tumor cells." (PMID 41263459, 2025). "Overexpression of DDX5 can attenuate ZC3H12D‐induced suppression of CCND1 mRNA in breast tumor cells." (PMID 41263459, 2025). "In the future, inducing ZC3H12D expression while suppressing DDX5 expression in breast tumors may be a promising strategy for targeted cell cycle therapy." (PMID 41263459, 2025). "Therefore, we proposed a model to elucidate the potential antagonistic roles of ZC3H12D and DDX5 in regulating the cell cycle progression of breast tumor cells." (PMID 41263459, 2025). "As expected, DDX5 promoted the G1/S cell cycle transition of breast tumor cells." (PMID 41263459, 2025). "The histologic analysis further revealed that the degree of CCND1 staining was lower (CCND1‐negative) in breast tumor tissues with high ZC3H12D staining (ZC3H12D‐positive), but greater CCND1 staining (CCND1‐positive) was observed in breast tumor tissues with greater DDX5 staining (DDX5‐positive)." (PMID 41263459, 2025). "In this study, we discovered that the RBPs ZC3H12D and DDX5 (DEAD‐box helicase 5) antagonistically regulate CCND1 mRNA stability and expression in breast tumor cells." (PMID 41263459, 2025). "Next, we explored the roles of DDX5 and ZC3H12D in breast tumor progression." (PMID 41263459, 2025). "In addition, DDX5 and ZC3H12D were also positively and negatively correlated with the expression of several cell cycle‐promoting genes, such as WEE1 and CDK2, in human breast tumor tissues." (PMID 41263459, 2025). "Notably, DDX5 and ZC3H12D could positively and negatively regulate the expression of CCND1, respectively, in human breast tumors." (PMID 41263459, 2025).
cholangiocarcinoma (2 papers, 2020 to 2022). A carcinoma that arises from the intrahepatic biliary tree (intrahepatic cholangiocarcinoma) or from the junction, or adjacent to the junction, of the right and left hepatic ducts (hilar cholangiocarcinoma). "Linc00473 sponges miR-506, preventing miR-506 from targeting DDX5, thus promoting the progression of cholangiocarcinoma." (PMID 35992805, 2022).
colorectal tumor (2 papers, 2009 to 2019). "We also demonstrated that O‐GlcNAcylation can mechanically increase the activation of the AKT/mTOR signalling pathway by regulating the expression of DDX5, thereby increasing the proliferation and metastasis of colorectal tumour cell lines." (PMID 30484950, 2019). "There are several examples of dyregulation of RNA helicases in cancer, mostly in the forms of overexpression including those of DDX5 and DDX6 which were reported to be overexpressed in colorectal tumor." (PMID 19161603, 2009).
endometrial cancer (2 papers, 2019 to 2022). Primary or metastatic malignant neoplasm involving the endometrium (mucous membrane that lines the endometrial cavity). "Correlation between the clinicopathological factors and the expression of HDGF and DDX5 in endometrial cancer." (PMID 31032220, 2019). "Therefore, we first knocked down DDX5 in endometrial cancer cells by siRNA, and found that the protein expressions of both c-MYC and PAX8 were reduced." (PMID 35672291, 2022). "Correlation between HDGF and DDX5 expression in endometrial cancer tissues." (PMID 31032220, 2019).
lung adenocarcinoma (2 papers, 2019 to 2023). A carcinoma that arises from the lung and is characterized by the presence of malignant glandular epithelial cells. "In previous study, our team had shown the interaction of β-catenin and HDGF or DDX5 in Lung Adenocarcinoma." (PMID 31032220, 2019).
lupus nephritis (2 papers, 2025). Glomerulonephritis in the context of systemic lupus erythematosus. "A similar pattern was also observed for DDX5, B2M, and TMSB4X in CKD/lupus nephritis, and for GATM in the control group." (PMID 39974940, 2025).
non-alcoholic steatohepatitis (2 papers, 2023 to 2024). "Transcriptomic analyses of HCCs from TCGA and the Stelic Animal Model (STAM) of non-alcoholic steatohepatitis revealed elevated expression of these interconnected pathways in the context of DDX5 downregulation." (PMID 39122708, 2024). "Interestingly, nonalcoholic steatohepatitis (NASH), a condition leading to HCC, is also linked to the downregulation of DDX5 mRNA levels by an unknown mechanism." (PMID 38036507, 2023).
Obesity (2 papers, 2015 to 2021). Accumulation of substantial excess body fat. "This unappreciated role of DDX5 in adipogenesis provides further insight into adipogenic molecular pathways, providing an additional potential target to address metabolic diseases including obesity and type 2 diabetes that are of increasing importance to global public health." (PMID 26637310, 2015). "In early obesity, inflammatory cues in CCs were mediated by the upregulation of genes involved in cellular response to stress as DEAD-box helicase 5 (Ddx5), hypoxia inducible factor 1 subunit alpha (Hif1a), and ADAM metallopeptidase domain 9 (Adam9)." (PMID 34805147, 2021).
pancreatic cancer (2 papers, 2023). "In other words, high DDX5 expression will decrease DNA instability by activating the DDX5-mediated DNA repair surveillance mechanism to reduce pancreatic cancer malignancy." (PMID 37596619, 2023). "Consistently, high DDX5 expression in pancreatic cancer tissues was correlated to high CD24 expression, while the PARylation activity of PARP1 was inversely correlated with CD24 expression." (PMID 37596619, 2023). "Thus, the study suggests that DDX5 is involved in immune checkpoint molecule CD24-mediated resistance in pancreatic cancer." (PMID 37596619, 2023). "PARP1 binds to, and inhibits DDX5 by ADP-ribosylating DDX5 in pancreatic cancer cells (Fig. 3C1), which can be abolished by PARP1 inhibitor, talazoparib, while PARP1 inhibition increased DDX5 expression and binding to the CD24 promoter." (PMID 37596619, 2023).
sarcoma (2 papers, 2022 to 2023). A usually aggressive malignant neoplasm of the soft tissue or bone. "SRSF3 regulates multiple cancer-related genes, including EP300, DDX5, and MAP4K4, to increase the proliferation of sarcoma cells." (PMID 37558679, 2023).
acute kidney injury (1 paper, 2023). Sudden and sustained deterioration of the kidney function characterized by decreased glomerular filtration rate, increased serum creatinine or oliguria. "miR-206 binds to DEAD-box helicase 5 (DDX5) to inhibit the activation of NLR family pyrin domain containing 3 inflammasome and alleviate acute kidney injury." (PMID 36845016, 2023).
Autoimmunity (1 paper, 2019). The occurrence of an immune reaction against the organism's own cells or tissues. "DDX5 was found to control the differentiation of Th17 cells at steady state and autoimmunity." (PMID 31632275, 2019).
autosomal dominant polycystic kidney disease (1 paper, 2022). Autosomal dominant form of polycystic kidney disease.
bladder cancer (1 paper, 2022). "Third, consistent with the finding that mKras is a downstream target of DDX5, our recent studies demonstrated that human bladder cancer cells with mKras are more sensitive to FL118 treatment when compared to tumour cells with wild‐type Kras." (PMID 35604033, 2022).
bunyavirus infection (1 paper, 2018). "Unlike MYXV, bunyavirus replication is unaffected by DDX5 silencing, so that the antiviral function of DDX5 remains undefined, as DDX5 depletion upregulated DDX17 expression, restricting bunyavirus infection in an interferon-independent manner." (PMID 29642538, 2018).
cerebral cavernous malformation (1 paper, 2021). A disorder characterized by malformations in the structure of the capillaries in the brain. "Mechanistically, CCM1, a gene mutated in cerebral cavernous malformation, suppresses DDX5, which regulates the suppression of YAP/TAZ signaling, indicating that CCM1 and DDX5 are novel upstream regulators of YAP/TAZ signaling." (PMID 33807895, 2021).
Cerebral ischemia (1 paper, 2022). Restriction of arterial blood supply to the brain associated with insufficient oxygenation to support the metabolic requirements of the tissue. "All in all, this study clarifies that circPUM1 mitigates cerebral ischemia-reperfusion-induced neuronal injury by targeting the microRNA-340-5p/DEAD-box helicase 5 axis." (PMID 35510394, 2022).
chronic hepatitis B (1 paper, 2021). "Given that the majority of our patients were those with chronic hepatitis B-induced HCC, similar to the other 2 reports, it implied that the role of DDX5 was likely to be tumor- and patient-specific, rather than those of underlying liver diseases." (PMID 33764710, 2021).
colitis (1 paper, 2020). Inflammation of the colon. "In intestinal epithelial cells (IECs), DDX5 promotes the expression of immune response genes and oncogenes posttranscriptionally and is a novel therapeutic target for treating colitis and intestinal cancers." (PMID 32817263, 2020). "In summary, DDX5 posttranscriptionally orchestrates intestinal RNA programs and drive colitis and intestinal cancers." (PMID 32817263, 2020). "Knocking out DDX5 in epithelial cells protected mice from intestinal tumorigenesis and dextran sodium sulfate (DSS)–induced colitis." (PMID 32817263, 2020).
developmental delay (1 paper, 2022). "As a member of the DDX5.Dbp2 subfamily, DDX59 has nine highly conserved sequences, the most characteristic regions including aspartate-glutamate-alanine-aspartate (D-E-A-D), which has been reported to be involved in malignancies, neurological development, and developmental delay." (PMID 36081993, 2022).
encephalitis (1 paper, 2020). An acute inflammatory process affecting the brain parenchyma. "The up-regulation of DDX5 could be another mechanism of viral-triggered cell activation, especially since this protein has been shown to promote the infection capability of encephalitis flaviviruses, which are also RNA viruses." (PMID 32244779, 2020).
Ewing sarcoma (1 paper, 2021). A small round cell tumor that lacks morphologic, immunohistochemical, and electron microscopic evidence of neuroectodermal differentiation. "YK-4-279 was initially reported as a small molecule targeting the interaction of oncogenic protein EWS-FLI1 with RNA helicases DHX9 and DDX5 in Ewing’s sarcoma." (PMID 34221969, 2021).
fibrosis (1 paper, 2024). the formation of excess fibrous connective tissue in an organ or tissue in a reparative or reactive process. "To elucidate the molecular mechanism of DDX5 in cartilage fibrosis and degeneration, we analyzed the AS events regulated by DDX5 in ATDC5 cells." (PMID 38760576, 2024).
heart failure (1 paper, 2025). Inability of the heart to pump blood at an adequate rate to meet tissue metabolic requirements. "In heart failure and cardiomyopathy, RBPMS cooperates with RBM20 to regulate splicing of sarcomeric genes such as TTN, safeguarding contractile integrity, while DDX5 maintains calcium homeostasis through CAMK2D splicing, and loss of QKI results in profound sarcomere disarray and heart failure." (PMID 41399527, 2025).
hepatitis B virus infection (1 paper, 2022). A viral infection caused by the hepatitis B virus. "Hepatitis B virus infection led to a surge in miR-17-92, which further impaired the expression of DEAD-Box helicase 5 (DDX5) by targeting its mRNA 3’-UTR." (PMID 35984196, 2022).
herpesvirus infections (1 paper, 2025). "It is fascinating to speculate if DDX5 and DDX17 would play similar proviral roles in other herpesvirus infections." (PMID 40257982, 2025).